HNRNPA2B1 (heterogeneous nuclear ribonucleoprotein A2/B1)
Diseases named in the same sentence as HNRNPA2B1 in open-access papers (continued):
Sharing a sentence is not in itself a finding about the gene and the disease.
tumor (continued). "Particularly, emerging evidence has demonstrated that hnRNPA2B1 regulates tumor proliferation and metastasis through the regulation of the AKT/mTOR signaling pathway." (PMID 37990246, 2023). "To summarize, knocking out HNRNPA2B1 significantly inhibited tumor growth and bone metastasis in vivo." (PMID 37215455, 2023). "By recognizing m6A sites for variable splicing, maintaining RNA stability, and regulating translation and transport, hnRNPA2B1 plays a vital role in various aspects of tumor development, metabolism, and regulation of the immune microenvironment." (PMID 37546413, 2023). "Overexpression of hnRNPA2B1 leads to the enrichment of tumor-derived extracellular vesicles (EVs) containing miR-378a-3p in prostate cancer bone metastases." (PMID 37546413, 2023). "The tumorigenic function of hnRNPA2B1 in vivo was determined by a subcutaneous tumor formation experiment and a HCC mouse model via tail injection of several plasmids into the mouse within 5s-7s." (PMID 38017546, 2023). "verified the mechanism of HNRNPA2B1 in tumor cells through immunohistochemistry and western blotting." (PMID 37020597, 2023). "Since HNRNPA2B1's general processing‐promoting effect on miRNAs and miRNAs' universal tumour‐suppressing silencing function, HNRNPA2B1 seemed to act as an oncogenic factor in various cancers." (PMID 36162823, 2023). "Consistent with the in vitro CCK-8 and colony formation assays, the results showed statistically significant differences demonstrating that knockout of HNRNPA2B1 inhibited xenograft tumor growth." (PMID 37215455, 2023). "Previous studies confirmed that hnRNPA2B1 plays crucial roles in the proliferation, migration, and drug resistance of multiple types of tumor cells." (PMID 37990246, 2023). "They found that the RNA-binding protein hnRNPA2B1 was in charge of the tumor suppressor miR-122-5p preferential processing and release into melanoma EVs." (PMID 36803831, 2023). "They found that the RNA-binding protein hnRNPA2B1 controlled the selective sorting and release of tumor-suppressor miR-122-5p into lung cancer EVs." (PMID 36803831, 2023). "Knockdown of CAND1 inhibited the growth of subcutaneous tumours in mice, while overexpression of hnRNPA2B1 partially reversed the inhibitory effect of CAND1 on tumour growth." (PMID 37837399, 2023). "In this review, we focused on recent researches regarding the biological behaviors and underlying mechanisms of hnRNPA2B1 in various aspects, including epithelial-mesenchymal transition (EMT), tumorigenesis, tumor microenvironment (TME), and tumor metabolism." (PMID 37546413, 2023). "What’s more, increased expression of miR-184-3p and decreased expression of Cd206 in tumor tissues in the miR-184-3p OE & hnRNPA2B1 KD group were confirmed by qRT-PCR, and the secretion of IL-10 detected by ELISA was also significantly reduced." (PMID 37957722, 2023). "Through the regulation of pyruvate kinase (PKM) splicing and the subsequent increase in PKM2 expression, hnRNPA2B1 exerts a tumor-suppressive effect on cellular glucose metabolism." (PMID 37546413, 2023). "Blocking with unlabeled hnRNPA2B1 antibody effectively lowered the tumor uptake of 64Cu-PCB-hnRNP at 4 h by 1/6-fold and 1/8-fold for LHS and RHS tumors, respectively." (PMID 36015303, 2022). "NSUN5 and HNRNPA2B1 expressions were higher in tumor tissues than in normal tissues, consistent with our other findings." (PMID 35571068, 2022). "These PET images clearly showed that the pretargeting strategy can be achieved by the hnRNPA2B1 antibody to visualize the tumor at an earlier time point with less background interference." (PMID 36015303, 2022).
tumor (continued). "The PET imaging also demonstrated the high tumor uptake of radioactivity mediated by hnRNPA2B1 within 1 h." (PMID 36015303, 2022). "During epithelial mesenchymal transition (EMT) in tumor cells, hnRNPA2B1 up-regulates vimentin and N-cadherin and down-regulates E-cadherin, promotes cell invasion and metastasis in various cancers." (PMID 36451863, 2022). "Knockdown of HNRNPA2B1 inhibits tumor cell progression of ESCA cells, indicating HNRNPA2B1 as an oncogenic protein in ESCA development." (PMID 35069736, 2022). "The tumor-to-muscle (T/M) ratio at 8 h p.i. was increased to exceptionally high 559 from 314 at 4 h p.i. in the 48 h pre-circulation of the hnRNPA2B1 conjugate." (PMID 36015303, 2022). "Prior to the administration of the 64Cu-PCB-hnRNP, the tumor was blocked by injecting excess hnRNPA2B1 mAb (19.2-fold) and at 4 h p.i. organs were harvested for the biodistribution studies." (PMID 36015303, 2022). "Compared to the conventional strategy using the ex vivo labeled hnRNPA2B1 antibody, the pretargeting strategy showed the higher tumor uptake with very minimal background noises." (PMID 36015303, 2022). "The 48 h pre-circulation of hnRNPA2B1 antibody increased tumor uptake by 25% compared to 24 h circulation." (PMID 36015303, 2022). "HNRNPA2B1 knockout increases BC cell apoptosis, alleviates autophagy, and declines tumor growth in vitro and in vivo." (PMID 35462896, 2022). "The PCR results showed that NSUN5 and HNRNPA2B1 expression was higher in tumor tissues than in normal tissues." (PMID 35571068, 2022). "Particularly, hnRNPA2B1, an hnRNP subtype, is an essential factor in tumor development and progression." (PMID 36015303, 2022). "With the development of high-throughput sequencing, sporadic studies have revealed that m6A regulators METTL3, FTO, and HNRNPA2B1 are aberrantly expressed in EC and affect the metastasis and invasion of a tumor by affecting the stability of mRNA." (PMID 36364436, 2022). "Together, our data suggested that HNRNPA2B1 promotes tumor progression of MM through the regulation of TLR4 expression." (PMID 36401285, 2022). "The tumor specificity of the hnRNPA2B1 antibody was successfully evaluated using a blocking study in the TNBC MDA-MB-231 tumor model." (PMID 36015303, 2022). "In particular, they found that high expression of ALKBH5 and, in particular, another m6A reader, HNRNPA2B1, correlated with tumor diameter and lymphatic metastasis and promoted disease by upregulating fatty acid synthesis enzymes, ACLY and ACC1." (PMID 34209046, 2021). "For example, the increased expression of HNRNPA2B1 leads to tumor suppression in multiple cancers, including pancreatic ductal adenocarcinoma, ovarian cancer, hepatocellular carcinoma, lung cancer, melanoma, glioblastoma, and prostate cancer." (PMID 33495416, 2021). "We found that METTL3, RBM15B, YTHDC2, YTHDF2, and HNRNPA2B1 were indeed highly expressed in the tumor samples." (PMID 34336856, 2021). "After the IHC was scored, the results indicated lower HNRNPA2B1 expression in normal cases and higher expression in tumor tissues and metastatic lymph node." (PMID 34631545, 2021). "The higher expression of YTHDF1, HNRNPC, IGF2BP1, VIRMA, and HNRNPA2B1, the more characteristics of tumor OV stem cells and the lower the tumor OV differentiation." (PMID 34150845, 2021). "To further confirm these results, we also performed sphere-forming assay, which showed that knocking out hnRNPA2B1 impaired the ability of these SW480 cells to form tumor spheres." (PMID 34630502, 2021). "hnRNPA2B1‐dependent H19 has been reported to be contained in exosomes, with a capacity to transfer gefitinib resistance to tumor cells." (PMID 33931980, 2021). "On this ground, we firstly analyzed hnRNPA2B1 CLIP-seq data of HepG2 tumor cells in ENCORI database to investigate its directly interacted transcripts." (PMID 34044823, 2021).
tumor (continued). "The results showed that HNRNPA2B1 was increased significantly in ESCA and positively associated with ESCA tumor stage and lymph node metastasis." (PMID 33748145, 2021). "Recent studies have revealed m6A methylation components can act as tumor-associated factors, including “writers” (METTL3/14, WTAP and KIAA1429), “erasers” (FTO and ALKBH5), and “readers” (YTHDF1/2/3, HNRNPA2B1, BCDIN3D)." (PMID 33791305, 2021). "The results indicated that the HNRNPA2B1 level was increased in the tumor diameter of ESCC tissues ≥5 cm compared with that <5 cm." (PMID 33134163, 2020). "Inversely, the expression of METTL14 and HNRNPA2B1 were relatively lower in tumor tissues (p = 0.0016, p = 0.0163 respectively)." (PMID 32219036, 2020). "HNRNPA2B1 affects the major hallmarks of cancer by promoting proliferative signaling, change of cellular energetics, and suppressing tumor-promoting inflammation and invasion and metastasis." (PMID 32322560, 2020). "Eventually, HNRNPA2B1, GOLGA8B and MAPK8IP3 were picked out to be significantly associated with tumour prognosis." (PMID 32485038, 2020). "The tumorigenic activities of hnRNPA2B1 in VHL-deficient cells were also disclosed with stimulatory effects on cell proliferation, migration, invasion and xenograft tumor growth in our results, which was previously proposed by several investigations." (PMID 32826868, 2020). "Some of the tumor suppressors and oncogenes regulated by HNRNPA2B1 include c-FLIP, BIN1, and WWOX, and the proto-oncogene RON." (PMID 33163396, 2020). "We also found that HNRNPA2B1 expression positively correlated with tumor diameter and lymphatic metastasis of ESCA." (PMID 33134163, 2020). "HNRNPA2B1 contributes in activating cyclo-oxygenase 2, which eventually leads to tumor growth, promoting EMT through ERK/SNAIL signaling reduced cell proliferation and prolonged S-phase and suppressed subcutaneous tumorigenicity." (PMID 32322560, 2020). "Most importantly, the oncogenic properties of hnRNPA2B1 downstream c-myc signaling and anti-tumoral feedback loop between hnRNPA2B1 and VHLα were consolidated with xenograft tumor in vivo." (PMID 32826868, 2020). "Our study found that HNRNPA2B1, GOLGA8B and MAPK8IP3 were identified to be tightly associated with tumour progression and prognosis, and further researches are needed before clinical application." (PMID 32485038, 2020). "Five m6A-related genes (ZC3H13, METTL14, YTHDF2, YTHDF3 and HNRNPA2B1) showed significantly downregulated in tumor tissue, while seven regulators (YTHDC2, FTO, WTAP, METTL3, ALKBH5, RBM15 and KIAA1429) was remarkably upregulated in ccRCC." (PMID 32419773, 2020). "Emerging evidence demonstrated that hnRNPA2B1 promotes tumor metastasis through extracellular regulated protein kinases (ERK) pathway." (PMID 32698890, 2020). "A synthetic analog of a chemical found in fruit suppresses tumor growth by targeting an RNA-binding protein (hnRNPA2B1) and preventing the production of a pro-cancer regulatory factor." (PMID 30755586, 2019). "LncRNA miR503HG, a host gene for the MIR503, specifically interacts with the heterogeneous nuclear ribonucleoprotein A2/B1(HNRNPA2B1), which suppresses metastatic tumor suppression through modulating the ubiquitination status of HNRNPA2B1." (PMID 31906046, 2019). "Highly augmented expression of SRSF1 by ~ 1.86 folds and hnRNPA2B1 by ~ 2.66 folds was noted in HepR21 cells which are in concurrence with the increased tumor potency in these cells compared to HepG2." (PMID 29535843, 2018). "Activation of K-Ras by interaction with the protein-coding gene heterogeneous nuclear ribonucleoprotein A2/B1 (HNRNPA2B1) is associated with upregulation of the mTOR signaling pathway and results in PDAC cell survival and tumor formation in mice." (PMID 29670543, 2018). "Heterogeneous nuclear ribonucleoprotein A2B1 (HNRNPA2B1) is closely related to tumour occurrence and development, oncogene expression, apoptosis inhibition and invasion and metastasis capacities." (PMID 28077929, 2017).
tumor (continued). "The RNA‐binding protein hnRNPA2B1 acts as an m6A reader and plays a role in tumor development." (PMID 39810713, 2025). "Furthermore, widespread expression of regulators like HNRNPC and HNRNPA2B1 supports their functional significance across diverse tumor microenvironments, while sparse or restricted expression of others suggests niche or indirect regulatory functions." (PMID 40565233, 2025). "The in vivo mice assay found that HNRNPA2B1 silencing repressed the tumor growth." (PMID 41271615, 2025). "However, in the presence of beraprost sodium, HNRNPA2B1 translocates to the nucleus and promotes miR-503 exosomal secretion, thereby exerting anti-tumor effects." (PMID 40703632, 2025). "Furthermore, we monitored the HOTTIP/hnRNPA2B1/DKK1 regulatory axis in tumor specimens derived from nude mice." (PMID 38481876, 2024). "Furthermore, the overexpression of hnRNPA2B1 increased tumor glucose uptake and lactate and pyruvate production in GC cells, but decreased the NADP+/NADPH ratios." (PMID 38887155, 2024). "HNRNPA2B1 also plays a role where circular RNA from the NEIL3 gene (known as circNEIL3) is packed into exosomes and transferred to tumor-associated macrophages within the tumor microenvironment." (PMID 38474421, 2024). "HNRNPA2B1, acting as the “reader” of m6A modification, can influence primary microRNA processing, mRNA metabolism, and transport, thus influencing immune cell infiltration and the development of the tumor immune microenvironment." (PMID 39268079, 2024). "In the light of the role of hnRNPA2B1 in modulating tumor metabolic reprogramming, we sought to investigate whether hnRNPA2B1 acts in modulating chemosensitivity in GC." (PMID 38887155, 2024). "hnRNPA2B1 can promote the progression of several tumour types by a variety of mechanisms." (PMID 37837399, 2023). "Moreover, many researchers have demonstrated that hnRNPA2B1 regulates tumor proliferation and metastasis through regulation of the AKT/mTOR signaling pathway." (PMID 37990246, 2023). "Similarly, a recent study reported that high expression of HNRNPA2B1 in late‐stage CRC (stages III and IV) was associated with tumor progression, metastasis, and poor prognosis." (PMID 37039257, 2023). "Moreover, results from a series of functional assays demonstrated that HNRNPA2B1 promoted tumor growth and metastasis." (PMID 37215455, 2023). "To clarify whether HNRNPA2B1 influences in vivo NSCLC tumorigenesis, we utilized sh-HNRNPA2B1 or sh-NC stably transfected 95D cells to construct the xenograft tumor models by subcutaneous injection into the flank of nude mice." (PMID 37308993, 2023). "hnRNPA2B1-knockout cells inhibited tumor formation in graft experiments." (PMID 38017546, 2023). "Consequently, discovering the novel role of hnRNPA2B1 in the tumor microenvironment opens up new avenues and ideas for future tumor immunotherapy." (PMID 37546413, 2023). "HNRNPA2B1 is highly expressed in multiple types of tumor tissues." (PMID 37671941, 2023). "Moreover, the patients with deeper tumor invasion depth presented higher hnRNPA2B1 expression (P = 0.015)." (PMID 37716979, 2023). "Overall, these results indicate that hnRNPA2B1 covers multiple metabolic imbalances in tumor cells." (PMID 37546413, 2023). "Increasing the expression of miR-184-3p in tumor cells while down-regulating hnRNPA2B1 to block its secretion through exosomes could most effectively inhibit tumor growth and metastasis." (PMID 37957722, 2023). "In summary, our study has revealed that hnRNPA2B1 promoted tumor cell growth and metastasis via exosomal sorting of tumor suppressor miR-184-3p in TNBCs, while the secreted exosomes in turn function to remodel the immunosuppressive microenvironment by inducing M2 polarization of macrophages." (PMID 37957722, 2023).
tumor (continued). "Furthermore, our results also demonstrated that oncogenic NUF2 functions as a tumor activator in OC progression by interacting with HNRNPA2B1 via the PI3K/AKT/mTOR signaling pathway." (PMID 36670423, 2023). "Overexpressing miR-184-3p in tumor cells and simultaneously knocking down hnRNPA2B1 to block its secretion through exosomes could effectively inhibit tumor growth and metastasis." (PMID 37957722, 2023). "The role of miR-184-3p and hnRNPA2B1 in tumor growth and metastasis was further assessed in vivo." (PMID 37957722, 2023). "All these results indicated that hnRNPA2B1 played an important role in the sorting of tumor suppressor miR-184-3p into exosomes, and blocking this process could effectively inhibit tumor growth and metastasis." (PMID 37957722, 2023). "Taken together, these results provided comprehensive evidence that hnRNPA2B1 could significantly contribute to the tumor growth and metastasis of CRC cells in vitro and in vivo, which suggested that hnRNPA2B1 was a clinically crucial oncogene in CRC." (PMID 37716979, 2023). "Moreover, we verified that hnRNPA2B1 mediated CAND1 function in tumour progression and lipid metabolism." (PMID 37837399, 2023). "The crucial role of hnRNPA2B1-mediated vesicle transport in tumor immunity is evident." (PMID 37546413, 2023). "Herein, we utilized the hnRNPA2B1 mAb for nuclear imaging of TNBC MDA-MB-231 tumor models." (PMID 36015303, 2022). "Moreover, we performed the Edu and CCK8 assays about the phenotypic effects of hnRNPA2B1 silencing on tumor cells." (PMID 35501306, 2022). "In our study, HNRNPA2B1 was positively correlated with activated CD4+ memory T cells and activated myeloid dendritic cells, implying that HNRNPA2B1 may enhance the efficacy of immunotherapy through regulating the tumor-infiltrating immune cells." (PMID 36189296, 2022). "METTL3 and HNRNPA2B1 expression was reduced in tumor xenografts with LINC01833 suppression." (PMID 35441574, 2022). "The results showed that the effects of hnRNPA2B1 knockdown was consistent with retention of tumor-suppressive miRNAs and could be partly attenuated by miR-1298-5p inhibitors." (PMID 35501306, 2022). "Some studies have shown that HNRNPA2B1 can promote tumor immunity and anti-tumor." (PMID 36189296, 2022). "Previous studies have demonstrated that HNRNPA2B1 may aggravate tumor progression by activating Wnt-β/catenin signaling via m6A." (PMID 36171892, 2022). "The function of HNRNPA2B1 in tumor immunity remains controversial." (PMID 36189296, 2022). "Four m5C/m6A-related gene signatures consisting of HNRNPA2B1, IGF2BP2, NSUN4, and ALYREF were used to construct a prognostic risk model, and the high-risk group had a worse prognosis, higher immune checkpoint expression, and tumor mutational burden (TMB)." (PMID 36246622, 2022). "In contrast, other studies have revealed that HNRNPA2B1 inhibits tumor immunity." (PMID 36189296, 2022). "Moreover, HNRNPA2B1, miR-17, miR-20a, miR-93, and miR-106b showed the higher expression in tumor tissues than tumor-adjacent tissues." (PMID 34277606, 2021). "The current results demonstrate that PCAT6 acted as a tumor activator in PCa progression by sponging miR-326 and increasing Hnrnpa2b1 expression and that the PCAT6/miR-326/Hnrnpa2b1 signaling might be a new therapeutic target for PCa." (PMID 34277403, 2021). "Taken together, these results suggested that HNRNPA2B1 might affect tumor-promoting signaling pathways by regulating the expression of the miR-17-92 cluster, leading to poor prognosis of ESCA patients." (PMID 34277606, 2021). "Notably, the gene most frequently associated with increased risk was HNRNPA2B1; in ESCA, the increased expression of this gene alone predicted poor prognosis by affecting tumor-promoting signaling pathways through miR-17-92 cluster." (PMID 34277606, 2021). "Also, HNRNPA2B1 was recognized as an oncogene as it promotes tumor growth and migration in various cancers." (PMID 34917507, 2021).